LEP (leptin)
Diseases named in the same sentence as LEP in open-access papers (continued):
Sharing a sentence is not in itself a finding about the gene and the disease.
breast cancer (continued). "In this study, we focused on the identification of a specific leptin-induced EV proteomic signature in MCF-7 breast cancer cells, and their possible impact on tumor biology, in attempt to find molecular effectors associated with breast cancer progression." (PMID 36361728, 2022). "However, it was previously shown that hypoxia through hypoxia-inducible factor-1α induced leptin mRNA and protein expression in breast cancer cells." (PMID 36381236, 2022). "Although the exact mechanism has not been defined, we observed that autophagy inhibition also reduced leptin-induced ERK phosphorylation in both breast cancer subtypes, probably suggesting ERK involvement in cell migration-associated events such as actin cytoskeleton rearrangement." (PMID 36291097, 2022). "The search for the role of leptin in the etiology of breast cancer dates to 1999." (PMID 36428526, 2022). "Leptin has been described as fostering tumor development through the activation of various signaling pathways, by stimulating the proliferation and growth of breast cancer cells, and by promoting angiogenesis, invasion, and metastasis." (PMID 36401194, 2022). "Additionally, in obese breast cancer patients, leptin expression has been reported to be higher in the adipose tissue neighboring the tumor than in the adipose tissue far from the tumor cells." (PMID 36077676, 2022). "Long-term exposure to leptin could markedly inhibit the sensitivity of breast cancer cells to the estrogen tamoxifen." (PMID 35701840, 2022). "Interestingly, in MCF-7 breast cancer cells, LEP has been demonstrated to be able to sustain, in a dose-dependent manner, the cancer cell immortalization by upregulating the expression of Human Telomerase Reverse Transcriptase (hTERT) via STAT3 dimerization." (PMID 36291602, 2022). "Of particular interest, converging data suggest that an increased leptin:adiponectin ratio is strongly associated with with TNBC rather than ER positive breast cancer." (PMID 36077676, 2022). "Indeed, IL-6, IL-8 and leptin secreted by ASCs promote invasion by breast cancer cells (MCF7, MDA-MB-231)." (PMID 36038791, 2022). "Furthermore, through the MAPK pathway activation, LEP promotes the growth of breast cancer in nude mice and induces the proliferation and migration of the MCF-7 BC cell line." (PMID 36291602, 2022). "Moreover, we evaluate the direct effect of the adipokine leptin in our cell model to prove the specificity of EV effect on MCF-7 breast cancer cell metabolism." (PMID 36361728, 2022). "Furthermore, leptin or TGF-β signal activation, which is frequent in breast cancer patients with obesity, is linked to lower ACC1 expression, which promotes EMT." (PMID 35736645, 2022). "However, in premenopausal women, leptin, the leptin-to-adiponectin ratio and CRP were inversely associated with breast cancer risk, while in postmenopausal women they were positively associated with breast cancer risk." (PMID 35430795, 2022). "The fact that a more robust phosphorylation could be observed in DSG-BC-2 derived from an obese patient is in agreement with the postulated role of leptin in the promotion of breast cancer cells in obese patients." (PMID 36591465, 2022). "In fact, a study suggested that levels of leptin could be used to predict type, grade, prognosis, and recurrence in breast cancer based on its immunohistochemical staining." (PMID 34212054, 2021). "Leptin increases the expression of inflammatory cytokines such as TNFα and IL-1β which contributes to tumour-associated inflammation and subsequently, immunosuppression of tumouricidal CD8+ cytotoxic T cells in breast cancer." (PMID 34572888, 2021). "We questioned whether adiponectin and/or honokiol can inhibit Med1 in leptin-exposed breast cancer cells." (PMID 34389732, 2021).
breast cancer (continued). "We reviewed the main findings recent years on the principal molecular actors that are involved in the interactions between MetS and breast cancer biology, including leptin, adiponectin, insulin and IGF-1, Angiotensin II and Calcium and, cholesterol and lipoprotein." (PMID 33842335, 2021). "High circulating estradiol was a poor prognostic factor and leptin may be a protection signal in Chinese postmenopausal patients with breast cancer." (PMID 34970222, 2021). "Moreover, the optimal growth of leptin-stimulated breast cancer cells has been observed in high glucose culture conditions." (PMID 33535537, 2021). "Furthermore, similar to leptin, resistin promotes the metastatic potential of breast cancer cells by inducing EMT and stemness." (PMID 34681797, 2021). "Considering the coexistence of autophagy activation and elevated FAO, we speculated that induction of FAO and ATP production by leptin in breast cancer cells might be ascribed to activation of autophagy." (PMID 33226729, 2021). "We observed a positive, although not significant, association between leptin and breast cancer, probably due to the small sample size and the weakness of the association." (PMID 34209441, 2021). "Furthermore, adiponectin can inhibit the proliferation, migration and invasion of breast cancer cells induced by leptin and has anti-tumor activity." (PMID 34485124, 2021). "To investigate whether leptin induces lipogenesis in breast cancer cells, we examined the effect of leptin on the expression of SREBP‐1, a master transcriptional regulator of fatty acid biosynthesis." (PMID 33226729, 2021). "Therefore, we assessed relationships between DP and high-molecular weight (HMW) adiponectin and leptin concentration among breast cancer survivors." (PMID 34684340, 2021). "The reasons for leptin advanced the development of breast cancer may be that leptin promoted the growth and proliferation and enhanced the invasion and metastasis of breast cancer cells via activating the JAK/STAT3 and PI3K/AKT signaling pathways." (PMID 34970222, 2021). "In addition, inhibition of FAO led to restoration of ATP levels in leptin‐treated breast cancer cells, indicating that leptin stimulates ATP generation in FAO‐dependent manner." (PMID 33226729, 2021). "We measured adiponectin and leptin with the automated ELLA platform and a manual commercially available enzyme-linked immunosorbent assay (ELISA) kit on serum samples of women enrolled in two international breast cancer prevention trials." (PMID 34209441, 2021). "In the present study, we examined the prognostic significance of LEP in breast cancer." (PMID 34414945, 2021). "Furthermore, the data obtained emphasizes the possibility of blocking the leptin/leptin receptor axis, as an adjuvant therapy in cats with luminal B and triple-negative mammary carcinoma subtypes, as reported for breast cancer patients." (PMID 33644151, 2021). "Leptin also elicits metabolic reprogramming in breast cancer." (PMID 33799880, 2021). "We further explored whether Med1 is the key node by which leptin interferes with tamoxifen-mediated growth inhibition of breast cancer cells." (PMID 34389732, 2021). "Conversely, a study presented that leptin was significantly related to poor prognosis in overall and tamoxifen-treated breast cancer patients, and may contribute to tamoxifen resistance through inducing increased nuclear expression of ERα." (PMID 34970222, 2021). "In addition, leptin inhibits apoptosis by downregulating pro-apoptotic genes in MCF-7 (ER-positive) breast cancer cells." (PMID 34944905, 2021). "Thus, we performed a systematic review and updated meta-analysis to obtain a more precise assessment of the association between PON1, LEP and LEPR polymorphisms and the risk of breast cancer." (PMID 34452542, 2021).
breast cancer (continued). "Accordingly, leptin overexpression is detected in breast cancer cells and neighboring adipocytes, contrasting with normal breast glandular epithelial cells, promoting the expression of several tissue factors, which suggest an oncogenic role for this adipocytokine." (PMID 33644151, 2021). "Collectively, these data suggest that alterations in leptin‐mediated fatty acid metabolism may contribute to the promoting effect of leptin on breast cancer cell growth." (PMID 33226729, 2021). "Therefore, the relationship between LEP and LEPR gene polymorphisms and expression of ER, PR, and HER2 receptors in women with breast cancer was evaluated." (PMID 33864589, 2021). "Third, through upregulation of FAO, leptin promotes breast cancer stemness and chemoresistance." (PMID 33535537, 2021). "The purpose of our study was to determine the prognostic value of LEP in breast cancer." (PMID 34414945, 2021). "As expected, we observed that inhibition of autophagy by pharmacological inhibitors or knockdown of autophagy‐related LC3B genes resulted in restoration of ATP levels and FAO rates in leptin‐treated breast cancer cells, indicating the crucial role of autophagy in FAO induction and ATP production." (PMID 33226729, 2021). "Breast cancer cells exposed to leptin showed a temporal increase in Med1 expression." (PMID 34389732, 2021). "Subgroup analyses from recent meta-analyses showed that leptin and adiponectin were strongly associated with breast cancer in Asians compared to non-Asians, in obese compared to non-obese subjects and postmenopausal compared to premenopausal women." (PMID 34209441, 2021). "Interestingly, a positive correlation was found between the leptin level and the incidence of breast cancer, which probably results from the proinflammatory, pro-angiogenic, and pro-carcinogenic activity of this protein." (PMID 33864589, 2021). "More recently, the inhibition of leptin signaling by LDFI confirmed the involvement of the leptin-mediated signaling pathway in the development of aromatase inhibitor (AI) therapy resistance in breast cancer." (PMID 34356668, 2021). "We tested whether leptin could increase the abundance of intracellular FFA to provide breast cancer cells with substrates for β‐oxidation." (PMID 33226729, 2021). "Leptin and the leptin receptors have been identified in malignant cells of various origins including hepatocellular cancer, colorectal cancer, thyroid cancer and breast cancer." (PMID 33987528, 2021). "Clinicopathological relationship of LEP mRNA expression in breast cancer." (PMID 34414945, 2021). "Leptin was reported to stimulate mitophagy to remove damaged mitochondria, which is speculated to mediate enhanced oxidative metabolism by leptin in breast cancer cells." (PMID 33535537, 2021). "Herein, we found that leptin enhanced formation of lipid droplets in breast cancer cells and autophagy inhibition mitigated this lipid accumulation, indicating that autophagy might be responsible for leptin‐induced lipogenesis." (PMID 33226729, 2021). "Dysregulation of the leptin/leptin receptor has been suggested to participate in the development of a large variety of malignancies, including breast cancer, pancreatic cancer, thyroid cancer, endometrial cancer, and gastrointestinal cancer, predominantly through the JAK/STAT pathway." (PMID 34156978, 2021). "In addition, increased leptin and IL-6 were observed in the blood serum of women with breast cancer." (PMID 33864589, 2021). "In breast cancer, leptin expression is significantly correlated with that of Ob-R." (PMID 34868066, 2021). "Additionally, we evaluated if the effect of autophagy on leptin-induced migration induced changes on EMT markers in breast cancer cells." (PMID 33763424, 2021).
breast cancer (continued). "The incidence of breast cancer in postmenopausal woman has been shown to rise as BMI increases, and adipokines released from the increased adipose tissue mass, in particular the adipocytokine leptin, are considered to be key drivers of breast cancer tumorigenesis." (PMID 34210055, 2021). "Furthermore, we discuss the potential crosstalk between the two most abundant adipokines produced by the adipose tissue (adiponectin and leptin) and the androgen receptor, an emerging marker in breast cancer." (PMID 34066328, 2021). "Thus, women with breast cancer have higher plasma leptin levels and RNA expression in adipose tissue than healthy subjects." (PMID 34573003, 2021). "In contrast, leptin, a 16 kDa protein, is a product of the obesity gene (Ob/Ob) which increases in concentration with adiposity and has a direct mitogenic action on breast cancer cells or acts indirectly to promote the production of estrogen-receptor and resistance to insulin." (PMID 34684340, 2021). "Leptin is expressed in normal breast tissue, breast cancer cells and solid tumors." (PMID 33842335, 2021). "Leptin signaling affects the progression of ER- breast cancer." (PMID 33842335, 2021). "Although, some researchers differ with a fact that leptin plays role in the breast cancer etiology." (PMID 34535145, 2021). "Moreover, leptin-activated JAK/STAT3 pathway also takes part in activating FAO through upregulation of CPT1B in breast cancer stem cells, which is critical for self-renewal and chemoresistance." (PMID 34888248, 2021). "LEP was downregulated in breast cancer tissues compared to levels in normal tissues." (PMID 34414945, 2021). "Studies in animal models using mice with genetically obese leptin-deficient Lep ob/ob or leptin receptor–deficient Ob-R db/db did not detect mammary tumors in either case, indicating that an intact leptin axis is essential for these tumors to develop." (PMID 34868066, 2021). "Interestingly, leptin downregulated the expression of CCN5 in breast cancer cells MCF-7 and ZR-75-1 cells via activating JAK/STAT and Akt pathways." (PMID 34588926, 2021). "We questioned whether leptin exposure affects phosphorylation and nuclear translocation of ER in breast cancer cells." (PMID 34389732, 2021). "It has been confirmed that ACAT2 could promote the proliferation, migration and invasion of breast cancer cells after being up-regulated by leptin, which might be a potential biomarker and precision treatment target." (PMID 34790227, 2021). "Over the past decade, several molecular epidemiological studies have been performed to identify the association of PON1 rs662, rs854560, LEP rs7799039G>A, and LEPR rs1137101 polymorphisms with susceptibility to breast cancer, but the findings have been conflicting." (PMID 34452542, 2021). "Leptin is also able to induce aromatase activity, thus potentiating ER signaling in breast cancer cells, and this may play a role in tumor progression." (PMID 34485137, 2021). "Additionally, the other research has recently suggested that leptin promotes breast cancer cell proliferation, migration, and invasion via the up-regulation of PI3K/AKT/SREBP2 signal pathway through acetyl-CoA acetyltransferase 2 (ACAT2)." (PMID 33935708, 2021). "Leptin appears to be a key driver in breast cancer tumorigenesis." (PMID 34868066, 2021). "Then we analyzed whether the leptin gene expression itself correlated with overall survival in a cohort of ER+ breast cancer patients." (PMID 34389732, 2021). "Increased inflammation may result in the formation of breast cancer, which also confirms the ability of leptin to promote angiogenesis in neoplastic cells." (PMID 34371845, 2021). "Although leptin differentially induced autophagy in the breast cancer cell lines tested, autophagy inhibition reduced leptin-induced cell proliferation in MCF7 cells and decreased cell migration, ERK activation, and impaired morphological changes in both cell lines." (PMID 33763424, 2021).
breast cancer (continued). "Yet, the contradictory results of FASN expression in breast cancer indicated in these two studies need further verification to see whether the effect of leptin varies in time-dependent or dose-dependent manner." (PMID 34888248, 2021). "Leptin levels are also correlated with different breast cancer types." (PMID 34588926, 2021). "The important role of leptin in breast cancer carcinogenesis and progression may influence the choice of aromatase inhibitors based on their distinct influence on adipokines like leptin in vivo." (PMID 34554372, 2021). "Indeed, we observed elevated Med1 expression in leptin-treated breast cancer cells and breast tumors developed in obese mice." (PMID 34389732, 2021). "Furthermore, the expression of leptin and its receptor Ob-R were positively correlated, suggesting that leptin acts on mammary tumor cells via an autocrine pathway." (PMID 34210055, 2021). "Also, elevated levels of phosphorylated EGFR and ERK were observed in leptin treated breast cancer cells compared to untreated cells." (PMID 34389732, 2021). "Finally, we have also demonstrated that all these effects of leptin on lipid metabolism and growth of breast cancer cell are driven by autophagy activation and SREBP‐1 induction." (PMID 33226729, 2021). "Studies conducted on leptin have shown that it may play a role in the occurrence and development of breast cancer." (PMID 35027962, 2021). "Additionally, leptin promotes ER+ breast cancer cell proliferation through modulation of estrogen levels and signaling." (PMID 33859943, 2021). "Autophagy could have a synergistic or antagonistic role in the tumor promoting effects of leptin in breast cancer, therefore we evaluated the role of autophagy in leptin-induced proliferation and migration in breast cancer cell lines." (PMID 33763424, 2021). "Several studies strongly support the hypothesis that serum leptin levels correlate with breast cancer occurrence and tumor behavior." (PMID 34485137, 2021). "In addition, leptin was found to increase cell proliferation in MCF-7 breast cancer cells via aromatase activation and JNK phosphorylation." (PMID 33804101, 2021). "Moreover, a number of studies have highlighted a link between leptin and the leptin receptor (Ob-R) overexpression with more aggressive breast cancer as evidenced by distant metastases, lymph node metastases, and increased tumor size." (PMID 34210055, 2021). "Therefore, leptin through binding to its receptor is involved in the tumorigenesis of breast cancer." (PMID 34210055, 2021). "Leptin inhibition has been tested as a therapeutic strategy mostly in breast cancer." (PMID 33671547, 2021). "Pooled data showed that PON1 rs662 and rs854560 polymorphisms were associated with risk of breast cancer in overall population, but not LEP rs7799039 and LEPR rs1137101." (PMID 34452542, 2021). "This study revealed that LDFI markedly inhibited mammosphere formation in metastatic breast cancer patient-derived cells, demonstrating how the inhibition of leptin signaling might represent an efficient approach to block cancer progression mediated by BSCM." (PMID 34356668, 2021). "The present review analyzes the role of leptin with respect to the immune system in breast cancer, mainly its relation to the activation of TILs and puts forward a new hypothesis on the association between the two." (PMID 34868066, 2021). "Interestingly, cats with mammary carcinoma present a decrease in the serum leptin/leptin receptor (ObR) ratio, as has been documented for pre-menopausal women with breast cancer." (PMID 34437486, 2021). "LEP expression was significantly decreased in invasive breast carcinoma (–16.434), breast phyllodes tumor (−21.654), mucinous breast carcinoma (–15.065), breast carcinoma (–15.496), and medullary breast carcinoma (–15.482)." (PMID 34414945, 2021). "Leptin decreased E-cadherin expression and increased vimentin expression in breast cancer cells." (PMID 32836215, 2020).